UMPS (uridine monophosphate synthetase)
Description:
Bifunctional enzyme catalyzing the last two steps of de novo pyrimidine biosynthesis, orotate phosphoribosyltransferase (OPRT), which converts orotate to orotidine-5'-monophosphate (OMP), and orotidine-5'-monophosphate decarboxylase (ODC), the terminal enzymatic reaction that decarboxylates OMP to uridine monophosphate (UMP).
Synonyms: OPRT; ODC
Tractability: Small molecule: an approved drug acts on it; a structure with a bound ligand is known; a high-quality ligand is known; it has a high-quality binding pocket; it belongs to a druggable protein family. PROTAC: ubiquitination databases record sites on it; its protein half-life has been measured; a small molecule that binds it is known.
Target class: Enzyme
Safety:
Unwanted effects reported when the protein is acted on. In parentheses: how it was acted on, where the effect was seen, and who reports it.
asthenia (source: ClinPGx)
drug toxicity (source: ClinPGx)
nausea and vomiting (source: ClinPGx)
Gene: Protein-coding gene on chromosome 3 (124,730,433 to 124,749,273, forward strand). Ensembl gene ENSG00000114491.
Subcellular location (Human Protein Atlas): Cytosol
Pathways (Reactome):
Metabolism: Pyrimidine biosynthesis
Gene Ontology:
Molecular function: orotate phosphoribosyltransferase activity; orotidine-5'-phosphate decarboxylase activity; protein binding
Biological process: UMP biosynthetic process; pyrimidine nucleobase biosynthetic process; 'de novo' CTP biosynthetic process; 'de novo' pyrimidine nucleobase biosynthetic process; 'de novo' UMP biosynthetic process; pyrimidine nucleotide biosynthetic process; UDP biosynthetic process
Cellular component: cytoplasm; nucleus; cytosol
Genetic constraint (gnomAD): Loss-of-function variants: 21 observed, 41.16 expected, observed/expected ratio (o/e) 0.51, 90% interval 0.36 to 0.74. The upper end of that interval is the gene's LOEUF score, 0.74, which puts it in group 3 of 6, group 1 being the genes least tolerant of losing a copy. Missense variants: 533 observed, 625.57 expected, observed/expected ratio (o/e) 0.85, 90% interval 0.79 to 0.92. Synonymous variants: 208 observed, 233.12 expected, observed/expected ratio (o/e) 0.89, 90% interval 0.8 to 1.
Homologues: Orthologues: chimpanzee UMPS (99% identical), macaque UMPS (98% identical), rabbit UMPS (92% identical), dog UMPS (92% identical), rat Umps (90% identical), mouse Umps (89% identical), pig UMPS (89% identical), guinea pig UMPS (86% identical), tropical clawed frog umps (66% identical), zebrafish umps (63% identical), Drosophila melanogaster r-l (47% identical), Caenorhabditis elegans umps-1 (39% identical).
Diseases named in the same sentence as UMPS in open-access papers:
UMPS is named in the same sentence as 52 diseases in open-access papers, as found by Europe PMC text mining. Sharing a sentence is not in itself a finding about the gene and the disease. The quoted sentences say what the papers report.
orotic aciduria (13 papers, 2017 to 2025). An extremely rare autosomal recessive inherited disorder caused by mutations in the UMPS gene. "Hereditary orotic aciduria is an autosomal recessive disease caused by deficiency of the uridine monophosphate synthase (UMPS) enzyme which catalyzes the last step in pyrimidine biosynthesis in mammals (EC 4.1.1.23)." (PMID 36999056, 2023). "For example, UMPS mutation at c.254T > C and c.1027 C > A causes UMPS-deficiency and results in hereditary oroticaciduria." (PMID 34638594, 2021). "Uridine monophosphate synthase deficiency (or hereditary orotic aciduria), due to biallelic mutations in UMPS, is a rare condition presenting with megaloblastic anemia in the first months of life." (PMID 28205048, 2017). "The typical disorder of pyrimidine metabolism is orotic aciduria, known as a megaloblastic anemia accompanied by renal impairment, due to a deficiency in uridine monophosphate synthetase (UMPS), a bifunctional enzyme in the de novo pyrimidine synthesis." (PMID 29375373, 2017). "In addition, heterozygosity for UMPS variants was recently found to be associated with mild asymptomatic orotic aciduria [OMIM#258900]." (PMID 36999056, 2023). "Similarly, rs1801019, for which we report a new significant association with orotate (p = 8.85 × 10−153), is a missense variant located within the fourth exon of the UMPS gene, whose mutations cause hereditary orotic aciduria." (PMID 35050183, 2022). "Additionally, pyrimidine metabolism disorders can cause some diseases, such as orotic aciduria, which results from uridine monophosphate synthase (UMPS) deficiency." (PMID 31232697, 2019). "Interestingly, family screening revealed heterozygous UMPS variants in combination with mild orotic aciduria in 19 clinically asymptomatic family members." (PMID 28205048, 2017). "Different symptoms are associated with orotic aciduria, a disorder of pyrimidine biosynthesis that take place in cattle, and people deficient in UMP synthase (UMPS)." (PMID 39434876, 2024). "We therefore conclude that heterozygous UMPS-mutations can lead to mild and isolated orotic aciduria without clinical consequence." (PMID 28205048, 2017). "The differential diagnosis of orotic aciduria (OA) is broad, and includes several treatable disorders, like urea cycle defects (especially ornithine transcarbamylase (OTC) deficiency) and uridine monophosphate synthase (UMPS) deficiency." (PMID 28205048, 2017). "Although the possibility of discovering other UMPS inhibitors could be considered, it may not prove to be safe in the clinic as loss of UMPS activity causes orotic aciduria." (PMID 33020720, 2020).
breast carcinoma (2 papers, 2020 to 2023). "We performed IHC staining of Meis1 and UMPS proteins in breast cancer tissues that were examined by ISH." (PMID 32382150, 2020). "SNORD3A enhances UMPS expression by sponging miR-185-5p to specifically promote chemosensitivity to 5-FU in breast cancer." (PMID 32382150, 2020). "As expected, Meis1 and UMPS protein were expressed at low levels in approximately 77.78% and 65.28% breast cancer specimens, respectively." (PMID 32382150, 2020). "High SNORD3A transcript and Meis1 and UMPS protein levels predicts a better outcome, but high miR-185-5p level predicts a worse outcome in breast cancer patients receiving 5-FU-based chemotherapy." (PMID 32382150, 2020). "Given that SNORD3A enhanced chemosensitivity to 5-FU depending on UMPS and that SNORD3A acts as miR-185-5p sponge to promote UMPS expression in breast cancer cells, we examined the involvement of miR-185-5p in SNORD3A-mediated chemosensitization to 5-FU." (PMID 32382150, 2020). "Together, these data suggest that SNORD3A may promote 5-FU sensitivity by activating UMPS expression in breast cancer cells." (PMID 32382150, 2020). "To determine whether SNORD3A enhancement of the sensitivity to 5-FU in breast cancer cells is dependent on UMPS, we stably knocked down UMPS in breast cancer cells with ectopic SNORD3A overexpression." (PMID 32382150, 2020). "Importantly, high SNORD3A transcript and Meis1 and UMPS protein levels predicts a better outcome, but high miR-185-5p level predicts a worse outcome in breast cancer patients receiving 5-FU-based chemotherapy." (PMID 32382150, 2020). "In breast cancer, SNORD3A sensitizes cells to chemotherapy by acting as a miRNA sponge for miR-185-5p, leading to uridine monophosphate synthetase protein upregulation." (PMID 37215987, 2023). "Collectively, these data suggested that miR-185-5p is highly expressed in breast cancer and that SNORD3A acts as a sponge to miR-185-5p to promote UMPS expression in breast cancer cells." (PMID 32382150, 2020). "In breast cancer tissues, SNORD3A level positively correlates with Meis1 and UMPS protein levels, whereas miR-185-5p level negatively correlates with UMPS protein level." (PMID 32382150, 2020). "Our results demonstrated that SNORD3A overexpression increased UMPS protein level but did not alter UMPS mRNA level in breast cancer cells." (PMID 32382150, 2020).
multiple myeloma (2 papers, 2019 to 2021). "The CERES score of four genes (ISG20, NDC1, SF3B3, UMPS) was significantly lower in the myeloma cell lines (n = 20) compared to in the other cancer cell lines (n = 769)." (PMID 34683129, 2021).
neuroblastoma (2 papers, 2021 to 2022). Neuroblastoma (NB) is the most common solid, extracranial childhood tumor. "This strong intercorrelation between CAD, DHODH, and UMPS was also evident in the subset of neuroblastoma cell lines." (PMID 35943801, 2022).
anemia (1 paper, 2019). A reduction in the number of red blood cells, the amount of hemoglobin, and/or the volume of packed red blood cells. "Anemia is a well‐known feature of another defect in the same pathway (uridine monophosphate synthase [UMPS] deficiency, UMPS, MIM #258900) and can be explained by the decreased red cell membrane stability due to lack of pyrimidines." (PMID 30681159, 2019).
asthenia (1 paper, 2023). Clinical sign or symptom manifested as debility, or lack or loss of strength and energy. "One study included in this review reported an association of the UMPS rs4678145 and rs2279199 SNPs with asthenia and severe nausea/vomiting in CRC patients treated with capecitabine-based regimens." (PMID 36980706, 2023).
colorectal tumors (1 paper, 2016). "RRM2 and UMPS upregulations and DPYD downregulation in colorectal tumors comply with the previous study." (PMID 27733154, 2016). "On the basis of our gene expression data we may generalize, that colorectal tumors irrespective of the stage and localization share common downregulation of DPYD and upregulation of PPAT, UMPS, RRM2, and SLC29A1 transcripts." (PMID 27733154, 2016).
glioblastoma (1 paper, 2020). The most malignant astrocytic tumor (WHO grade IV). "Western blot analysis indicated that DHODH and UMPS protein levels were higher in the glioblastoma cells LN229, GBM9, and SF188 in comparison to normal human p14ARF-/- immortalized astrocytes, which are non-transformed differentiated glial cells." (PMID 33201894, 2020). "In this study, we show that enzymes necessary for the de novo biosynthesis of pyrimidines, DHODH and UMPS, are elevated in high grade gliomas and in glioblastoma cell lines." (PMID 33201894, 2020). "By analyzing The Cancer Genome Atlas (TCGA) and the Chinese Glioma Genome Atlas (CGGA), we found that the mRNA levels of the enzymes in the de novo pyrimidine pathway, DHODH and UMPS, were elevated in high-grade glioma (IV/glioblastoma) patient samples." (PMID 33201894, 2020). "Moreover, our lab recently discovered that the transcription factor aryl hydrocarbon receptor (AHR), which is necessary for glioblastoma growth, mediates the expression of DHODH and UMPS in MYC-overexpressing fibroblasts and glioblastoma cells." (PMID 33201894, 2020).
immune deficiency (1 paper, 2025). "In the process of GSEA results of the four diagnostic genes (APRT, ARG1, UMPS, and LDHB) suggested that these four diagnostic genes were mainly enriched in mitochondrial gene expression, primary immune deficiency, other energy metabolism-related functions, and immune-related pathways." (PMID 40774030, 2025).
liver cancer (1 paper, 2018). An epithelial or non-epithelial malignant neoplasm that arises from the liver. "Intriguingly, CAD is also associated with unfavorable survival in liver cancer and renal cancer, and it catalyzes the rate-limiting step of the de novo PS pathway, suggesting it may be expressed at higher levels than DHODH and UMPS in de novo PS to ameliorate chemotherapy induced genotoxic damage." (PMID 30038717, 2018).
lung carcinoma (1 paper, 2024). "In particular, the inhibition of UMPS enzymes by this combination treatment was identified as one of the most effective strategies for inducing the apoptosis in lung cancer cells." (PMID 38704578, 2024). "In addition, there has been little study regarding UMPS inhibitor in lung cancer treatment." (PMID 38704578, 2024). "Collectively, these results suggest that the inhibition of UMPS by SH003 and DTX treatment is not a key factor in targeting all lung cancer types, and that a clearer molecular target needs to be identified to predict the effect of the combination." (PMID 38704578, 2024).
lung squamous cell carcinoma (1 paper, 2024). "In gene expression analysis by GEPIA, UMPS expression in NSCLC patient tissues was higher than in normal tissues, which exhibited a particularly significant difference in lung squamous cell carcinoma (LUSC)." (PMID 38704578, 2024).
medulloblastoma (1 paper, 2020). A malignant, invasive embryonal neoplasm arising from the cerebellum. "The roles of ACTL6A, EIF4A3, ENAH, and UMPS in medulloblastoma had not been reported." (PMID 33101383, 2020).
metastatic prostate carcinoma (1 paper, 2025). A carcinoma that arises from the prostate gland and has spread to other anatomic sites. "The eight genes where higher expression was associated with worse prognosis (CYC, CYP51A1, DHFR, EBP, KIF15, PPM1D, SQLE, and UMPS) represent potential additional therapeutic targets in metastatic prostate cancer." (PMID 40405591, 2025).
ovarian carcinoma (1 paper, 2015). A malignant neoplasm originating from the surface ovarian epithelium. "Besides, gene UMPS ranked second was involved in pathway of aminoacyl-tRNA biosynthesis, further suggests that UMPS could be related to a certain ovarian cancer." (PMID 26228058, 2015).
Sepsis (1 paper, 2025). Sepsis is defined as life-threatening organ dysfunction caused by a dysregulated host response to infection. "Consistent clustering of Sepsis samples in GSE65682 dataset was conducted based on four diagnostic genes (APRT, ARG1, UMPS, LDHB) associated with patient survival." (PMID 40774030, 2025). "•Identified 4 diagnostic genes (APRT, ARG1, UMPS and LDHB) for sepsis prognosis." (PMID 40774030, 2025). "Four diagnostic genes (APRT, ARG1, UMPS and LDHB) with excellent diagnostic value were identified, which might be mainly concentrated in energy metabolism-related functions and the immune-related pathway in the Sepsis process." (PMID 40774030, 2025). "APRT, ARG1, UMPS, and LDHB might be new ideas for studies related to the diagnosis and treatment of Sepsis." (PMID 40774030, 2025).
cancer (25 papers, 2006 to 2025). A tumor composed of atypical neoplastic, often pleomorphic cells that invade other tissues. "Regarding pyrimidine metabolism, the upregulation of CMPK1, CMPK2, CTPS2, CAD, DHODH, and UMPS suggests a role in supporting placental growth under stress, reflecting their established functions in cancer cell proliferation." (PMID 40825832, 2025). "It has been reported that the uric acid present at physiological concentrations in HPLM directly inhibits uridine monophosphate synthase (UMPS), an enzyme involved in pyrimidine biosynthesis, impacting in the metabolism of cancer cells." (PMID 38172668, 2024). "HPLM had profound effects on abundance of amino acid, lipid, and nucleotide metabolism, redox state and glucose utilization of cancer cells.Presence of uric acid in HPLM lead to inhibition of de novo pyrimidine synthesis enzyme UMPS, reducing sensitivity of cancer cell lines to 5-FU." (PMID 39355125, 2024). "Indeed, uric acid is tenfold higher in human blood than in culture media and mice serum and can inhibit uridine monophosphate synthase (UMPS), and consequently reduces the sensitivity of cancer cells to the chemotherapeutic agent 5-fluorouracil." (PMID 31319822, 2019). "A small-scale study in 23 GC patients indicated that UMPS polymorphisms are not related to cancer risk in Caucasian GC patients." (PMID 25992311, 2015). "The enzymes orotate phosphoribosyl-transferase (OPRT), uridine monophosphate synthetase (UMPS), and UMP kinase (UMPK) are crucial for the transformation of 5-FU into active metabolites that exert anti-cancer effects in tumor cells." (PMID 41276852, 2025). "Orotate phosphoribosyl-transferase (OPRT), uridine monophosphate (UMP) synthetase (UMPS) and UMP kinase (UMPK) are responsible for the conversion of 5-FU into active anti-cancer metabolites in tumor cells." (PMID 35740594, 2022). "De novo pyrimidine biosynthesis involves cytosolic carbamoyl-phosphate synthetase II, aspartate transcarbamylase, and dihydroorotase, uridine monophosphate synthetase (UMPS), and DHODH, contributing to ferroptosis resistance in cancer cells (e.g., HeLa cells) and in xenograft models." (PMID 38844964, 2024). "Prior studies have shown that cancer cells grown in HPLM not only utilize uridine for nucleoside salvage, but they also suppress de novo pyrimidine synthesis by uric acid-mediated inhibition of UMPS activity, decreasing sensitivity to pyrimidine synthesis inhibitors like 5-FU22." (PMID 40738904, 2025). "Even though this decreasing trend in the amplified transcription of SAMHD1 at 24 h might result in loosening the regulation of CAD, DHODH and UMPS, the critical enzymes involved in direct influx of dTMP (TYMS and TYMP) did not appear to be recovered to normal levels in cancer cells." (PMID 36414668, 2022).
infection (16 papers, 2012 to 2025). The state of being infected such as from the introduction of a foreign agent such as serum, vaccine, antigenic substance or organism. "The T. brucei null mutants were unable to induce any robust infection in mice model, suggesting the essentiality of UMPS in the T. brucei parasite; however, there were occasional reports of infected mice with UMPS null mutants." (PMID 29422065, 2018).
tumor (16 papers, 2008 to 2025). "In the PPI network, DHODH was found to interact with UMPS and CAD to form enzyme complexes, facilitating pyrimidine biosynthesis in cells, thereby promoting DNA synthesis to regulate tumor cell proliferation and inhibit ferroptosis." (PMID 38796629, 2024). "A number of specific enzymes (e.g., dihydroorotate dehydrogenase (DHODH) and uridine monophosphate synthetase (UMPS)) are known to be responsible for this process, as their activity allows ribosomal DNA transcription to be maintained in tumor cells." (PMID 36291824, 2022).
UMPS also shares sentences with these, for which no sentence is quoted: colorectal cancer (6 papers); gastric cancer (3); colon cancer (2); malaria (2); megaloblastic anemia (2); metabolic disorder (2); metastatic colorectal cancer (2); rectal cancer (2); Salmonella Infections (2); salmonellosis (2); adenocarcinoma (1); bacteremia (1); brain tumor (1); cholangiocarcinoma (1); colon adenocarcinoma (1); colorectal adenocarcinoma (1); COVID-19 (1); diarrhoea (1); genetic disorder (1); glioma (1); head and neck carcinoma (1); head and neck squamous cell carcinoma (1); leishmaniasis (1); leukemia (1); lymphoblastic leukemia (1); mitochondrial neurogastrointestinal encephalopathy (1); pancreatic cancer (1); pyrimidine metabolism disorders (1); renal carcinoma (1); squamous cell carcinoma (1).
A further 3 diseases each share a sentence with UMPS in 1 paper.